TNF (tumor necrosis factor)
Diseases named in the same sentence as TNF in open-access papers (continued):
Sharing a sentence is not in itself a finding about the gene and the disease.
Chronic colitis (continued). "In the absence of T-bet, particular microbes trigger overproduction of colonic TNF-α, which drives chronic colitis that is mediated by innate lymphoid cells preferentially producing IL-17A." (PMID 23063332, 2012). "Conversely, both 5-ASA and monotropein could substantially decrease the expression of TNF-α and IL-6 and increase the expression of IL-10 in mice with chronic colitis." (PMID 40041493, 2025). "Indeed, a recent study reported that animals with chronic colitis had a parallel increase in the cytokine levels of TNF-alpha, IL-1-beta, IL-6 and IL-10 in their blood and hippocampus." (PMID 35269413, 2022). "In addition, the anti-TNF-α efficacy of the CMV-siRTNF-α circuit was validated in a TNBS-induced chronic colitis model." (PMID 36171212, 2022). "Detection of the cytokine concentrations in the supernatant (five samples per group) revealed that IL-1β, IL-6, IL-12p70, TNF-α, and IL-23 were significantly decreased in the chronic colitis + Se-enriched L. acidophilus group compared with the chronic colitis group (P < 0.05)." (PMID 34532332, 2021). "A decrease in the severity of chronic colitis was also observed with intravenous administration of the drug at a dose of 1 mg/kg and was demonstrated to be comparable to a similar dose of antibodies against TNF-α (0.03 mg/mouse)." (PMID 33498456, 2021). "TNF-α is associated with CRC progression, and blocking TNF-α reduces the likelihood of colorectal carcinogenesis associated with chronic colitis." (PMID 30543324, 2018). "Intra-gastric delivery of an anti-TNF-α VHH constructs using an orally administered engineered Lactococcus lactis (L. lactis) significantly reduced inflammation in dextran sulfate sodium-induced chronic colitis mice." (PMID 29312310, 2017). "Similarly to what has been reported for several experimental models of acute and chronic colitis, local NO-production drives an increased expression of TNF-α, IFN-γ and IL-6." (PMID 24873968, 2014). "Mice developed chronic colitis characterized by a typical immune cell infiltration composed of T-lymphocytes and macrophages, with high levels of gene and protein expression of the proinflammatory cytokines interleukin-1β and tumor necrosis factor-α." (PMID 22848392, 2012). "Use of other models that are TNF-dependent or driven by induced T cell responses will be necessary to determine if LMP-420 may have efficacy in maintaining remission of chronic colitis driven by TNF or T cells." (PMID 18331642, 2008). "In addition, our study revealed a negative correlation between the levels of β-hydroxybutyrate in rats with chronic colitis and proinflammatory cytokines such as TNF-α, IL-6, IL-1β, and IL-18, with a strong tendency towards a positive correlation with IL-10 levels." (PMID 37513865, 2023). "In another chronic colitis model of IL-10−/− mice investigating prophylactic as well as therapeutic treatment regimens with SC doses ranging from 0.01–10 mg/kg, reductions in histopathology scores and TNF-α as well as interferon-gamma (IFN-γ) levels measured in colonic organ cultures were seen." (PMID 32545207, 2020). "In addition, it could ameliorate Th1-mediated chronic colitis and disordered immune state in IL-10(−/−) mice by inhibiting TNF-alpha/TNFR2 signal pathway." (PMID 32293395, 2020). "Interestingly, although vaccine A induced slightly higher levels of IL-18-specific IgG than vaccine D, mice immunized with vaccine A did not have any improvement in inflammatory scores, amounts of soluble collagens and IFN-γ, TNF and IL-18 levels in colon tissue in both acute and chronic colitis." (PMID 31428451, 2019). "Evidence suggests that IL‐6 is a key cytokine in chronic colitis, and reduced IL‐10 activity leads to increased levels of IL‐6, IFN‐γ, and TNF." (PMID 40953838, 2025). "After the induction of chronic colitis, a substantial elevation in the levels of iNOS, COX-2, TNF-α, IL-6, and IL-1β were observed in this study." (PMID 37891901, 2023).
Chronic colitis (continued). "The intervention of TFA increased the levels of IL-10 and TGF-β, and downregulated the expression of pro-inflammatory factors IL-17, IL-6, TNF-α, and IFN-γ in TNBS-induced chronic colitis." (PMID 35002710, 2021). "A trend towards a linear dose–effect correlation was observed in a chronic colitis model with doses ranging from SC 0.25–12.5 mg/kg, showing significant effects on DAI, histopathology scores and colonic TNF-α mRNA levels." (PMID 32545207, 2020). "In contrast, B. lactis LA804 which was less efficacious in the acute model was the most protective against chronic colitis by downregulating the expression of genes for CXCL2, IL-1β and TNF-α in TNBS-treated mice." (PMID 31035617, 2019). "Enzyme-linked immunosorbent assay (ELISA) revealed lower protein levels of pro-inflammatory cytokines, including TNF-α, IL-1β and IFN-γ, in colon tissues of mice with DSS-induced acute and chronic colitis that received HQT." (PMID 27982094, 2016). "Colorectal mRNA levels of inflammatory cytokines TNF-α, IL-1β, IL-6, MCP-1, and CSF-1, and COX-2, were measured in mice with chronic colitis." (PMID 27557503, 2016). "For all three cytokines assayed, mice that received TNBS showed increased levels when compared with normal mice (P’s < 0.01 for TNF and IL-17 levels and P < 0.05 for IFN- γ in chronic colitis)." (PMID 25756273, 2015). "In chronic colitis (63 days), MP did not affect the TNF-α, IL-β, IL-6 and IL-10 blood levels, which is consistent with our data." (PMID 40863977, 2025). "The data from the present study also showed that the plasma levels of proinflammatory cytokines, G-CSF, IL-6, IL-17, TNF-α, and CXCL1, were significantly increased in mice with chronic colitis, suggesting the presence of significant systematic inflammation in mice with chronic colitis." (PMID 36009796, 2022). "In the present study, significant increases in the production of IL-6, IL-12p70, IL-1β, TNF-α, IFN-γ, IL-21, and IL-17A and decreases in the production of IL-10 were observed in the chronic colitis group compared with the control group, and these changes were restored by NAM treatment." (PMID 33748287, 2021). "In our results, we established a refined and translationally relevant model of DSS chronic colitis in C57BL/6 mice and found morbidity in liver morphology and significant increases in proinflammatory cytokines (TNF-α, IL-1β, and IL-6) in the liver tissue of IBD mice." (PMID 33029104, 2020). "Furthermore, TNF has been shown to suppress LRH-1 and thereby reduce local GC synthesis in sustained chronic colitis." (PMID 31316505, 2019). "However, the high Th1 cytokines (IL-12, IFN-γ, IL-1, and TNF-α) and Th17 cytokine (IL-17) productions were observed in colon of the DSS-induced chronic colitis model." (PMID 30539029, 2018). "Results demonstrated that administration of PADF (10 mg/Kg/day) to mice with DSS chronic colitis significantly reversed the colon shortening, reduced the histological damage, neutrophil infiltration (as showed by MPO activity assay), and the production of inflammatory cytokines (IL-1β and TNF-α)." (PMID 32033338, 2020). "In chronic colitis, colon Cav-1 levels were significantly and inversely correlated with colon inflammatory scores in (P < 0.0003, r = -0.828), and also inversely correlated with IL-17 and TNF, but not IFN, levels (P < 0.01; r = -0.641 for IL-17; P < 0.02, r = -0.624 for TNF)." (PMID 25756273, 2015). "Besides TNF-α, another inflammation factor, IL-6, whose expression was elevated in macrophages with AEG-1 overexpression, was also reported contributing to the creation of an inflammatory environment and resulting in a chronic colitis and invasive colonic adenocarcinomas." (PMID 27793010, 2016).
memory impairment (99 papers, 2012 to 2025). "Second, the cross-sectional design precludes any conclusions about causality between elevated TNF-α levels and immediate memory impairment in patients with MDD." (PMID 41392773, 2025). "Elevated levels of TNF-α in the hippocampus are associated with neuroinflammation and memory impairment in AD mice models." (PMID 38396950, 2024). "Central upregulation of TNFα has been linked to dopaminergic neuron death, cognitive dysfunction, memory impairment, and disruption of the BBB, facilitating the entry of leukocytes into the CNS." (PMID 39772122, 2024). "As a response to the infection, proinflammatory cytokines are released and several studies suggest that TNFα, IL-1β, and IL-6 are significantly increased during infections and can cause learning and memory impairments." (PMID 39772122, 2024). "In this work, LPS has been found to be a contributing factor in learning and memory impairments; a finding associated with an increase in the amount of IL-6 and TNF-α, but a drop in IL-10 of the hippocampus." (PMID 31579451, 2019). "Inflammatory cytokines, including IL-6, IL-1β, and TNF-α, have been reported to be associated with learning and memory impairment." (PMID 28373844, 2017). "In summary, our research indicates that restoring the balance between TNFα/PGRN in the brain can ameliorate memory impairment caused by sleep deprivation." (PMID 28300056, 2017). "Overproduction of IL-6 and TNF-α were related to memory impairment, which were considered a histopathological hallmark of various neurological diseases in the brain." (PMID 24422705, 2014). "Blocking nerve injury-induced hippocampal TNF-α via oral administration of magnesium L-threonine, a new method of preventing neuropathic pain caused by chemotherapy or using nanocurcumin can improve pain and memory impairment." (PMID 35806192, 2022). "The observed lead‐induced increase in the concentration of TNF‐α and IL‐1β may be associated with the induction of neuroinflammation‐induced memory impairment." (PMID 34087957, 2021). "IL-6, IL-1β, and TNF-α have been reported to be associated with learning and memory impairment." (PMID 28373844, 2017). "Several studies have revealed that inflammatory cytokines like interleukin-6 (IL-6) and tumor necrosis factor-alpha (TNF-alpha) significantly affect memory impairment." (PMID 39906616, 2025). "Consistent studies have underscored the protective and anti-inflammatory effects of CA and has been shown to decrease TNF-α levels in the hippocampus and mitigate LPS-induced memory impairment." (PMID 39910608, 2025). "Another study revealed that ketogenic diet intervention reduced social deficits, repetitive behaviors, memory impairments, and inflammatory markers such as TNF-α, IL- 1β, and IL- 6 in BTBR rats." (PMID 40259156, 2025). "Memory impairment; notable neuroinflammation, including astrocyte and microglial activation; and elevated protein levels of IL‐1β, TNF‐α, and IL‐6 in the hippocampus were detected in the Pg and Pg OMV groups." (PMID 39932228, 2025). "VPA led to decreased COX-2, prostaglandin E2, NF-kB, and TNF-α expression in the brain after 30 days of treatment in a rat model of chemotherapy-induced memory impairment." (PMID 40806813, 2025). "Males: ↑ monokine expression (IFN-γ, TNF-α, IL-10 and IL-13) and memory impairment compared to females." (PMID 39126053, 2024). "To investigate the inhibitory effect of lupeol on memory impairment via preventing neuroinflammation, we determined the protein expressions of p-NFκB and TNF-α by western blot analysis." (PMID 39050141, 2024). "Our research findings suggested that learning and memory impairment induced by NDEA was associated with high levels of Aβ1-42, TNF-α, and IL-6 in the hippocampus, and these effects were recovered by metformin." (PMID 37759689, 2023). "Pre-treatment with incensole acetate, a crucial ingredient of frankincense reduced TNF-α and amended LPS-induced learning and memory impairments in rats." (PMID 37427333, 2023).
memory impairment (continued). "It was found that daily received lactobacilli (L. rhamnosus, L. reuteri, and L. plantarum) can prevent Lipopolysaccharide-induced (LPS-induced) elevated TNF-α mRNA expression in hippocampus and memory impairment." (PMID 37771706, 2023). "PKR activation occurs in a TNFα-dependent manner and this, in turn, results in IRS1 inhibition, synaptic loss and memory impairment." (PMID 34986876, 2022). "Scopolamine induced memory impairment and inflammation by activating various inflammatory mediators such as Aβ/NF-κB/TNF-α/COX-2/IL-18, and PGE2 along with oxidative stress." (PMID 36544525, 2022). "It has been found that berberine can reduce the levels of NF-κB, TLR4, TNF-α, and IL-6 in the brain of adult male cognitive impairment rats induced by lipopolysaccharide and prevent learning and memory impairment." (PMID 35795239, 2022). "For example, necroptosis mediates TNF-α-induced toxicity of hippocampal neurons, leading to memory impairment in AD." (PMID 35806192, 2022). "Salidroside potentially reduces hippocampus-dependent memory impairment by reducing Aβ1-42 deposition, microglial activation, and expression of proinflammatory factors, such as TNF-α, IL-6, and IL-1β, in the brain." (PMID 36014776, 2022). "In this study, we observed that melatonin treatment reduces the over‐production of IL‐1β and TNF‐α, and prevents neuroinflammation and memory impairment in the lead‐induced experimental rats." (PMID 34087957, 2021). "Huperzine A, a natural acetylcholinesterase (AChE) inhibitor, suppresses the overexpression of TNFα and protects against 2VO-induced memory impairment." (PMID 34030135, 2021). "In our study, the inflammatory processes observed as an increase of TNF-α level stay in line with the LPS-induced memory impairment observed in the PA test." (PMID 33579030, 2021). "For example, it has been demonstrated that the release of TNF-α and IL-1β is a sign of neuroinflammatory-induced memory impairment." (PMID 31231221, 2019). "Altogether, results suggest that ZIKV infection leads to elevated brain levels of TNF-α, microglial activation and increased expression of C1q and C3, culminating with synapse damage and memory impairment in adult mice." (PMID 31488835, 2019). "Similarity, in a colitis model, elevated NF-κB is detected in intestines as well as hippocampal zone with cooperative expression of TNF-α, which leads to serious memory impairment." (PMID 30823925, 2019). "In a literature review reported that transgenic rodents that overexpressed TNF-α exhibited inflammation and neurodegeneration, which lead to memory impairment." (PMID 30618732, 2018). "It has been reported that chronic administration of scopolamine for 14 days increased the expression of pro-inflammatory factors such as IL-1β and TNFα and inflammation is a proposed mechanism for scopolamine-induced memory impairment." (PMID 29942435, 2018). "Previous DIO animal models have also demonstrated an association between HFD consumption and elevated neuroinflammatory markers, such as TNF-α and IL-1β, following demonstrated memory impairments on the T-maze and Y-maze." (PMID 30619085, 2018). "In this study, SPS induced an increase in the levels of the proinflammatory cytokines TNF-α and IL-6 and produced learning and memory impairment." (PMID 29973144, 2018). "Blocking these exaggerated effects, specifically by decreasing the release of tumor necrosis factor α (TNF-α), interleukin 1β (IL-1β), and interleukin 6 (IL-6), has been shown to prevent inflammation-induced memory impairment." (PMID 29167670, 2017). "Given the role of PGRN and TNFα signaling in S-DEP-induced memory impairment, we predicted that manipulation of this signaling would affect spine density." (PMID 28300056, 2017). "Microglial activation stimulates the accumulation of pro-inflammatory cytokines, such as IL-1β, IL-6, and TNF-α, which are responsible for memory impairment induced by LPS." (PMID 27803668, 2016).
memory impairment (continued). "For instance, it has been shown that TNF-α and IL-6 are critical for neuroinflammation-induced memory impairment." (PMID 24886300, 2014). "TNFα is an important mediator for learning and memory impairment after surgery." (PMID 40011296, 2025). "It was reported that ketogenic diet reduces social deficits, repetitive behaviors, memory impairments and inflammatory markers such as TNF-α, IL- 1β and IL- 6 and may be a therapeutic approach in autism spectrum disorder." (PMID 40259156, 2025). "Furthermore, rutin modulates the production of pro-inflammatory cytokines by decreasing TNF-α and IL-1β generation in microglia and enhances the memory in scopolamine-induced memory impairment in zebrafish by enhancing cholinergic neurotransmission." (PMID 41471791, 2025). "Further, doxepin prevented stress-induced memory impairments and decreased TNF-α levels in the rat hippocampus, if administered 1 mg/kg intraperitoneally for 21 days, but not for 5 mg/kg or 10 mg/kg concentrations, pointing toward a concentration-dependent effect." (PMID 36979303, 2023). "Additionally, EA stimulation in Aβ25-35-treated rats can downregulate IL-1β and TNF-α in the prefrontal cortex and hippocampus, attenuating inflammatory responses and improving memory impairment." (PMID 38274501, 2023). "Also, a significant positive high linear correlation between the level of TNFα (r = 0.753, *p < 0.05), interleukin 1β (r = 0.739, *p < 0.05) in prefrontal cortex and long-term memory impairment in diabetic mice in passive avoidance test (PA) was observed." (PMID 35468904, 2022). "In addition, TNF-α crosses the BBB and activates TNF-α receptor 1 in astrocytes, causing hippocampal synaptic alterations and memory impairment." (PMID 35736871, 2022). "Furthermore, etanercept, a TNF-α inhibitor, rescued the working memory impairment accompanied by a reduction in hippocampal TNF-α." (PMID 35782423, 2022). "Interestingly, similar to IL-6 and IL-18, TNF-α is also a product of activated microglia and is known to enhance memory impairment in mouse models of AD." (PMID 35648273, 2022). "This study demonstrated that AH might ameliorate the scopolamine-induced memory impairment by protecting the cholinergic system via inhibition of NF-κB signaling pathways and decreased levels of TNF-α and IL-6 in liver tissue." (PMID 34445062, 2021). "Given the similarity of the neuroinflammatory process and neuronal death-related pathology in AD and VaD, we raised the question of whether anti-TNF-α treatment can ameliorate memory impairments and microglia-based neuroinflammation in a VaD model." (PMID 34030135, 2021). "Previous studies showed that pro-inflammatory cytokines, such as TNFα, IL6, and IL1β, could potentially disturb the Aβ clearance and cause memory impairments." (PMID 32867800, 2020). "Also, an increase in TNF-α appears to contribute to memory impairment by inhibition of long-term potentiation (LTP - persistent increase in synaptic strength following a high-frequency stimulation of a chemical synapse), via NMDA receptors." (PMID 34589875, 2020). "Studies indicate that microbiota disturbance leads to increased NF-κB activation and TNF-α expression with induced memory impairment in animal models, and the restoration of microbiota composition alleviates neuroinflammation in hippocampus and ameliorates relevant symptoms." (PMID 30823925, 2019). "It is important to note that NKA plays a significant role in central inflammation, which is apparent in diabetic rats, where inflammation-associated increases in tumor necrosis factor (TNF)-α and IL-1β, as well as decreased NKA activity, result in memory impairment." (PMID 26909067, 2016). "Previous studies also demonstrated that moxibustion could inhibit chemotaxis and cell migration into inflamed tissues by promoting neutrophil apoptosis and downregulating cytokines, such as IL-1β, IL-17, IFN-γ, and TNF-α, to improve inflammatory status and memory impairments." (PMID 38274501, 2023).